KRAS (KRas proto-oncogene, GTPase)
Diseases named in the same sentence as KRAS in open-access papers (continued):
Sharing a sentence is not in itself a finding about the gene and the disease.
lung cancer (continued). "In clinical studies, gefitinib induces initial tumor regressions in lung cancer patients with EGFR activating mutations, including Exon19 Del, L858R mutation, and has no significant anti-tumor activity in lung cancer patients with KRAS mutation." (PMID 23842453, 2013). "KRAS mutant lung cancers are generally refractory to chemotherapy as well targeted agents." (PMID 22654667, 2012). "Furthermore, KRAS and EGFR mutations have been detected in circulating tumour cells from patients with metastatic colon and lung cancer respectively." (PMID 22978632, 2012). "KRAS is downstream of EGFR, and hence tumors that contain KRAS mutations were found to be resistant to EGFR TKIs which makes KRAS a good marker for patients who should be excluded from EGFR TKI treatment and are accepted for gene testing of lung cancer." (PMID 26316937, 2012). "mir-25 and miR-21 are upregulated in EGFR mutation positive tumors, which are typically found in lung cancer never-smoker cases, while KRAS mutation positive tumors are associated with miR-495 up-regulation." (PMID 22852089, 2012). "EML4-ALK, EGFR, and KRAS mutations were all mutually exclusive, suggesting that ALK mutation may be an important oncogenic factor, and a potential therapeutic target in EGFR wild-type and KRAS wild-type lung cancer." (PMID 21444946, 2011). "For instance, EGFR pathway is frequently activated by gene mutations in nonsmoker lung cancers, while mutations of KRAS often occur in smoker lung cancer." (PMID 22174919, 2011). "These genes were expressed at comparable levels in lung carcinomas irrespective of the status of KRAS mutations." (PMID 21637843, 2011). "For advanced colorectal and lung cancers, patients currently are screened for mutations in the KRAS gene as therapy targeting EGFR is not effective when these tumors harbor mutations in the pathway downstream of EGFR." (PMID 21072204, 2010). "However, we did not detect an obvious correlation between mutational expression of EGFR, BRAF, PI3KI, or KRAS and sensitivity to AZD6244 or MK2206 in the lung cancer lines we tested." (PMID 21124782, 2010). "It is important to note that the GEPR generated in lung cancer cell lines and was not dependent on either KRAS or EGFR mutation status." (PMID 19439077, 2009). "A549 is an extensively studied lung cancer cell line and is known to have KRAS mutation but not any EGFR kinase domain mutations." (PMID 19238632, 2008). "Furthermore, mutant KRAS activates the NF-κB pathway, which leads to the upregulation of various cytokines and chemokines, such as IL-6, which plays a role in immune suppression in KRAS-driven lung cancer." (PMID 40333779, 2025). "Finally, we included 10 well-known cancer-related genes (or their hotspot-containing exons) listed as most frequently mutated in lung cancer (BRAF,EGFR,ERBB2,HRAS,KRAS,MAP2K1,MET,NF1,NRAS, and RIT1) in the panel to serve as internal controls for highly mutated regions." (PMID 40867048, 2025). "Furthermore, considerable progress has been made in the development of targeted KRAS inhibitors in recent years, with two KRAS inhibitors already approved by the Food and Drug Administration for use in non–small cell lung cancer, and multiple others in clinical trials." (PMID 40662372, 2025). "Similarly, in KRAS-mutant lung cancers, WEE1i and mTORi exhibited synergistic antitumor effects." (PMID 40885709, 2025).
lung cancer (continued). "The LUAD dataset lacked mutational profiling such as EGFR, ALK, or KRAS status, which are key determinants of prognosis in lung cancer and could influence spatial associations with survival." (PMID 40723219, 2025). "However, contrary to previous studies indicating that the combination of MAPK and CDK4/6 inhibitors induces RB protein-mediated cellular senescence and SASP activation, thereby enhancing NK cell immune surveillance and leading to the death of KRAS-mutant lung cancer cells." (PMID 40181456, 2025). "Furthermore, KRAS mutations have been linked to the upregulation of the immune checkpoint molecule PD-L1, suggesting that CRISPR-mediated knockout of PD-1 or PD-L1 could improve the efficacy of immunotherapies in KRAS-mutant lung cancers." (PMID 39820726, 2025). "Therefore, treatment of KRAS-mutant lung cancer remains a challenge." (PMID 39960727, 2025). "Research by Kostyrko's team at the University of California, USA, has discovered that knocking out UHRF1 can inhibit the growth of KRAS-driven mouse lung cancer tumors, suggesting that UHRF1 may become a potential therapeutic intervention target for KRAS-driven cancers." (PMID 40083325, 2025). "KRAS mutation‐positive non‐small cell lung cancer (NSCLC) was associated with an increased risk of VTE (OR: 2.67) compared to NSCLC patients without KRAS mutation, and ROS1 or ALK fusion‐positive NSCLC had a higher incidence of thromboembolisms than in EGFR mutated NSCLC." (PMID 39783855, 2025). "The very same molecular mechanism was implicated in the negative effect of Rocaglamide A on ERK pathway activity in KRAS-driven lung cancer, although the picture might be somewhat complicated by the finding that KRAS oncogene expression could be eIF4F-dependent, at least in some tumor types." (PMID 39436655, 2024). "While these conditions are poorly understood, they may account for the preference of KRAS mutations in the pancreas, colon and lung cancer but not in skin and oral carcinomas." (PMID 38963974, 2024). "In summary, these data suggest that KRAS-mediated inhibition of tumor-intrinsic IFNγ responses, which is required for effective antitumor immunity, may contribute to immune evasion in KRAS-mutant lung cancer." (PMID 38635884, 2024). "Research indicates that patients with KRAS G>T substitutions may have improved progression-free and overall survival compared to those with G>C or G>A substitutions, possibly reflecting distinct biological behaviors in KRAS-driven lung cancers." (PMID 39682234, 2024). "However, KRAS-mutant lung cancer was resistant to BETi, and it may limit BETi monotherapy in SMARCA4-UT which is usually accompanied by KRAS mutation." (PMID 38347129, 2024). "We also uncovered significant sex bias in transcription factor targeting of oncogenes and tumor suppressor genes, including AKT2 and KRAS that suggests lung cancer drugs targeting these genes might exhibit differences between the sexes in both efficacy and toxicity." (PMID 39107837, 2024). "Consequently, in the absence of STK11, lung cancers harboring KRAS mutations not only gain a growth advantage due to the unrestrained signaling of mTOR but also exhibit mitochondrial dysfunction, resulting in aggressive behavior." (PMID 39046176, 2024). "However, FASN remodels oxidised phospholipids to escape ferroptosis in KRAS-mutant lung cancer." (PMID 38228715, 2024). "Immunoblot analysis showed that the protein expression levels of HOXC10 in mouse lung cancer spine metastatic tissue were significantly higher than those in adjacent normal tissue, reinforcing the general role of HOXC10 in response to different KRAS mutant variants." (PMID 39191757, 2024).
lung cancer (continued). "As effective strategies to combine KRAS inhibitors and immunotherapies have so far proven elusive, a better understanding of the mechanisms by which oncogenic KRAS drives immune evasion is needed to identify approaches that could sensitize KRAS-mutant lung cancer to immunotherapy." (PMID 38635884, 2024). "However, a study by Zhu and colleagues found that menin may also function as a tumor promoter in KRAS-driven lung cancer in some contexts." (PMID 39336822, 2024). "However, the most common KRAS mutations in PDAC are G12D (44%), G12V (34%) and G12R (20%) that are not amenable to treatment by KRAS G12C-directed cysteine-reactive KRAS inhibitors such as Sotorasib and Adagrasib that exhibit clinical efficacy in lung cancer." (PMID 38686056, 2024). "Although some of these genes may be considered driver mutations, we designated this group the ‘no-driver-mutation group’ since, besides KRAS, none were proven drivers in lung cancer." (PMID 37751214, 2023). "Additionally, for ovarian cancer it was shown that TERT and MYC, as well as PIC3CA, CCNE1, and KRAS, might be useful to tailor therapeutics in precision medicine, and the same might be true for lung cancer." (PMID 37858127, 2023). "Notably, S713 phosphorylation in KRAS-mutant A549 lung cancer cells seems to be critical for the stability of CHD3 protein, as S713A mutation dramatically inhibited CHD3 protein expression, whereas the phosphorylation mimicking mutation S173D resulted in increased protein expression." (PMID 36858798, 2023). "In mouse lung cancer driven by the KRAS gene, ROS, which is required for the growth of cancer, is mainly produced in mitochondrial metabolism and the deletion of mitochondrial transcription factor A could disrupt mitochondrial function and decrease tumor incidence." (PMID 36982777, 2023). "Taken together, these findings suggest that the heightened activation of YAP, as observed in EGFR- or KRAS-mutated lung adenocarcinoma, as well as BRAF-mutant lung cancer cells and KRAS-mutant NSCLC tumors, might play a significant role in conferring resistance to MEK inhibition." (PMID 37569866, 2023). "Interestingly, we found that STK11 mutation status in lung cancer did not correlate with increased dependency on KRAS." (PMID 37141389, 2023). "ZNF304 is not highly expressed in lung tumors and its expression is significantly anti-correlated with UHRF1 expression in lung adenocarcinoma patients carrying a KRAS mutation, suggesting that UHRF1 may instead mediate this phenotype in KRAS-driven lung cancer." (PMID 37407562, 2023). "Of note, UHRF1 was not included in the CRISPR DepMap libraries nor in the genome-wide CRISPR library used in our previous work, therefore we were unable to establish if complete knock-out of UHRF1 in 2D could be a dependency in KRAS mutant lung cancer cell lines." (PMID 37407562, 2023). "Therefore, NF1 mutations should not always be considered a poor biomarker in lung cancer, similar to mutations in the KRAS gene." (PMID 35702826, 2023). "Our results, based on human and mouse cell lines, suggest that the MEKi and mtPKCi combination may be effective in a large spectrum of mut KRAS lung cancers regardless of the type of KRAS mutation or additional concurrent alterations in tumor suppressor genes." (PMID 37816716, 2023). "STK11 and KEAP1 mutations do not seem to influence the prognosis in KRAS wildtype lung cancers." (PMID 38067288, 2023). "Thus, the development of specific NOP56 inhibitors in combination with mTOR inhibitor therapy may be an effective strategy for the treatment of KRAS-mutant lung cancer in the future." (PMID 36741964, 2023).
lung cancer (continued). "The parallel analysis of both KRAS and let-7a may represent a new lung cancer–predictive biomarker." (PMID 37511536, 2023). "KRAS mutations in lung cancer also increase the expression of Acyl-coenzyme A synthetase long chain family member 3 (ACSL3) to reprogram lipid metabolism, promote Monounsaturated fatty acids-phospholipids (MUFA-PL) biosynthesis and ferroptosis resistance, and facilitate lung cancer progression." (PMID 38273826, 2023). "Interestingly, in a conditional knockout mouse model, HK2 mediated KRas-driven lung carcinoma and ErbB2-driven generation and maintenance of breast cancer, and HK2 downregulation inhibited lung cancer in vitro and in vivo as well as the malignant biological behavior of breast cancer." (PMID 37854321, 2023). "However, the mutational status of KRAS has neither prognostic nor predictive value in human lung cancer, limiting the possibilities to anticipate patient survival and to adapt treatments." (PMID 36163168, 2022). "Tan and his partners showed that bosutinib could repress the KRAS mutant lung cancer cells." (PMID 35844536, 2022). "The position of these inhibitors in the KRAS G12C lung cancer treatment strategy algorithm is still evolving; primarily, the activity of KRAS G12C may be limited due to the genetic heterogeneity and complex biology of KRAS." (PMID 36012655, 2022). "PD-L1-enhancing oncogenes, such as EGFR, ALK, MET, AKT, MYC, and CDK5, were not identified as hits in this study because KRAS mutations in lung cancer cell lines (H2009 and H460) could establish distinct PD-L1 regulatory axes." (PMID 36357569, 2022). "Although the mutation rate of KRAS G12C is less than 5% in Chinese lung cancer population while that in PDAC is less than 1% 140, it still brings promising treatment efficacy to the patients, which seems to open a new pattern of clinical research on KRAS mutated tumors." (PMID 36118526, 2022). "Any association of KRAS-G12C in smokers, whether current or ex-smokers, versus never smokers could not be verified among mCRC patients, in contrast to lung cancer where KRAS-G12C has been associated with smoking, especially in women." (PMID 35251991, 2022). "Finally, to test whether 249C could inhibit autophagy and attenuate the growth of mutant KRAS-dependent cancers as a single agent in vivo, we evaluated 249C in a mouse xenograft model of lung cancer (NSCLC, A549)." (PMID 35879364, 2022). "In KRAS-driven colorectal cancers, mitochondrial inhibitors, such as tigecycline, have been shown to reduce tumor growth in vivo, which suggests that this combination may yield positive results in lung cancers." (PMID 36230484, 2022). "In KRAS-mutant lung cancer cells, RAD51 may facilitate DNA damage repair and promote cell survival." (PMID 36164607, 2022). "In a meta-analysis, Mao and colleagues showed an ORR of 3% (6/210) in patients with mutant KRAS NSCLC and of 26% (287/1125) in KRAS wt lung cancers, fulfilling the hypothesis that KRAS mutations represent negative predictive biomarkers for tumor response in NSCLC patients treated with EGFR-TKIs." (PMID 36077640, 2022). "Additionally, recent findings in lung cancer have found that RB1 and p16/CDKN2A are activated by trametinib, and have implicated RB status in sensitivity to MEK inhibitors in KRAS mutant lung cancer cells; however, the underlying processes responsible for this observation remain poorly understood." (PMID 36418460, 2022).
lung cancer (continued). "Our data demonstrated that mutational activation of KRAS robustly promoted BCL6 expression, and genetic depletion of BCL6 exhibited a profound inhibitory effect on KRAS-driven lung tumorigenesis, suggesting that BCL6 is a lynchpin for oncogenic KRAS dependence in lung cancer." (PMID 36377663, 2022). "Although lung cancer cell lines have not been reported to be sensitive to proteasome inhibition, a case study did report exceptional therapeutic benefits of bortezomib in a KRAS-mutated lung adenocarcinoma patient." (PMID 35088066, 2022). "Among the RAS family, KRAS is the most abundant oncogene related to uncontrolled cellular proliferation to generate solid tumors in many types of cancer such as pancreatic carcinoma (over 80%), colon carcinoma (40–50%), lung carcinoma (30–50%), and other types of cancer." (PMID 35409064, 2022). "Therefore, when administering immunotherapy to patients with KRAS mutated lung cancer, attention needs to be paid to the differences in the TME of patients with lung cancer while paying attention to the heterogeneity in the efficacy of immunosuppressive agents." (PMID 35070984, 2021). "In this study, those findings were reproduced using a 3rd lung cancer model that is wild-type to both EGFR and KRAS oncogenes, thereby confirming the wider efficacy of inhaled topotecan against tumors that vary based on the two most common cancer-driver oncogenes in lung cancer." (PMID 33860729, 2021). "Indeed, the MET pathway was shown to be upregulated in KRAS-mutant lung cancer after MAPK inhibition and after treatment with KRAS inhibitors, an effect that could be enhanced by mutant MET." (PMID 34684076, 2021). "Based on the proteomics results and a preliminary CRISPR screen, the authors designed a dual knockout CRISPR library where they could target 119 proteins containing strong KRAS interactors and proteins suspected to be involved in KRAS transformation of lung cancer cells." (PMID 33562401, 2021). "Furthermore, the up-regulation of ACSL3, which has recently demonstrated to be essential for tumorigenesis in KRAS-driven lung cancer, may also be involved in activating mitochondrial respiration from fatty acids." (PMID 33806075, 2021). "Interestingly, SDPR was the only DEG that decreased in KRAS-mutant tumor tissues based on GEO datasets (GSE18784, GSE49200), which suggested that the downregulation of SDPR might be a specific signature during the development of KRAS-mutant lung cancer." (PMID 33435990, 2021). "Etiologically, KRAS-mutant lung tumors are associated with a current or former smoking history (mostly KRAS(G12C)), but KRAS mutations are also found with a different mutational spectrum (mostly KRAS(G12D)) in up to 15% of never-smokers who develop lung cancer." (PMID 33809660, 2021). "Thus, our clinical data further confirmed that LKB1 loss increased the DNA methylation and expression level of ALKBH5, which resulting in the demethylation of m6A modification on SOX2, SMAD7, and MYC, and maintaining their expression for KRAS mutant lung cancer." (PMID 34016959, 2021). "Because mutant KRAS-driven lung cancers are largely resistant to therapy, ISR inhibitors like ISRIB are promising agents for the treatment of this common deadly mutant KRAS-driven malignancy and may be applicable to other common cancers with KRAS mutations." (PMID 34330898, 2021). "Thus, we identified BLT2 as a potential contributor to KRAS-driven lung cancer, and our results may facilitate the development of strategies against KRAS-mutant lung cancer." (PMID 34635780, 2021).